IRGQ (immunity related GTPase Q)
Description:
Autophagy receptor that specifically promotes clearance of misfolded MHC class I molecules by targeting them to the lysosome for degradation. Acts as a molecular adapter that specifically recognizes and binds (1) misfolded MHC class I molecules following their ubiquitination, as well as (2) autophagy-related proteins, promoting the recruitment of misfolded MHC class I molecules to autophagy machinery for degradation. Degradation of misfolded MHC class I molecules is essential to prevent accumulation of defective MHC class I complexes at the surface of CD8(+) T-cells and prevent a stronger T-cell-mediated response. In contrast to other members of the family, does not show GTPase activity.
Synonyms: IRGQ1; FKSG27
Tractability: PROTAC: its protein half-life has been measured.
Gene: Protein-coding gene on chromosome 19 (43,584,367 to 43,596,145, reverse strand). Ensembl gene ENSG00000167378.
Subcellular location: Lysosome; Cytoplasmic vesicle, autophagosome
Subcellular location (Human Protein Atlas): Vesicles
Gene Ontology:
Molecular function: GTP binding; GTPase activity; protein binding; protein-macromolecule adaptor activity
Biological process: positive regulation of autophagy; protein quality control for misfolded or incompletely synthesized proteins; substrate localization to autophagosome
Cellular component: autophagosome; lysosome
Genetic constraint (gnomAD): Loss-of-function variants: 14 observed, 20.7 expected, observed/expected ratio (o/e) 0.68, 90% interval 0.45 to 1.06. The upper end of that interval is the gene's LOEUF score, 1.06, which puts it in group 4 of 6, group 1 being the genes least tolerant of losing a copy. Missense variants: 792 observed, 801.67 expected, observed/expected ratio (o/e) 0.99, 90% interval 0.93 to 1.05. Synonymous variants: 418 observed, 401.3 expected, observed/expected ratio (o/e) 1.04, 90% interval 0.96 to 1.13.
Homologues: Orthologues: chimpanzee IRGQ (99% identical), macaque IRGQ (97% identical), dog IRGQ (85% identical), guinea pig IRGQ (83% identical), mouse Irgq (77% identical), rat Irgq (77% identical), pig IRGQ (69% identical).
Diseases named in the same sentence as IRGQ in open-access papers:
IRGQ is named in the same sentence as 3 diseases in open-access papers, as found by Europe PMC text mining. Sharing a sentence is not in itself a finding about the gene and the disease. The quoted sentences say what the papers report.
cervical cancer (1 paper, 2025). A primary or metastatic malignant neoplasm involving the cervix. "Subsequently, the downregulation of IRGQ inhibited ferroptosis to promote the malignant proliferation of cervical cancer cells." (PMID 39836502, 2025). "Thus, our findings provide an innovative insight into the role of IRGQ in the malignancy of cervical cancer." (PMID 39836502, 2025).
IRGQ also shares sentences with these, for which no sentence is quoted: autoimmune disease (1 paper); hepatocellular carcinoma (1).